TNF (tumor necrosis factor)
Diseases named in the same sentence as TNF in open-access papers (continued):
Sharing a sentence is not in itself a finding about the gene and the disease.
melanoma (continued). "In monocyte-derived DCs (moDC), interleukin 12 (IL-12) and tumor necrosis factor alpha (TNF-α) production and co-stimulatory molecule expression is impaired after co-culture with melanoma cells, but it can be easily restored by pre-treatment with BRAFi." (PMID 32731406, 2020). "In these cells, altered expression of ADAM9 controls TIMP-1 expression and TNF-α/sTNFR1 pathway leads to modulation of melanoma cells proliferation and apoptosis." (PMID 32906814, 2020). "In contrast, for immunotherapies that repress an immune response, e.g., tumor necrosis factor (TNF) inhibitors for RA or checkpoint inhibitors for melanoma, the efficacy is reportedly greater for males than females." (PMID 32366281, 2020). "Previous research showed that TNF-α as one of the pro-inflammatory cytokines can function as potent inducers of melanoma cell plasticity in the context of T cell immunotherapy." (PMID 32742470, 2020). "For instance, the Ségui’s laboratory reported that TNFR1 mediates the Activation-Induced Cell Death (AICD) of CD8+ melanoma-specific tumour infiltrating lymphocytes (TILs) and that combining anti-TNF and anti-PD-1 promotes the regression of murine melanoma." (PMID 32365592, 2020). "To assess the role of ITCH in TNFα-triggered BRAF activation, we found that p-MEK and p-ERK were refractory to TNFα treatment in ITCH-depleted melanoma cells." (PMID 31015455, 2019). "And the adoptive transfer of TNF-α-treated Th9 cells induces more potent inhibition on melanoma tumor growth than regular Th9 cells in mouse models." (PMID 30717817, 2019). "In another study, intra-tumor injection of an oncolytic adenovirus coding for murine TNF, and IL-2 also promoted anti-PD-1 efficacy in mouse melanoma." (PMID 31417576, 2019). "Then, we examined the effects of TNFα (10 ng/mL), dcAMP (1 mM), and H89 (10 μM) on melanoma cell lines." (PMID 31611597, 2019). "Because of the toxicity of TNFα, it is mainly applied locally, for instance in isolated limb perfusion to treat advanced melanoma and sarcoma." (PMID 31709774, 2019). "The shared genes principally enriched in cytokine and TNF signaling (bladder, breast, colon, kidney, liver, melanoma, and sarcoma), epithelial cell signaling, carbon metabolism (esophagus, lung, prostate, and thyroid), and PI3K-Akt signaling pathway (ovary)." (PMID 29843204, 2019). "Treatment with 2HF at 50 or 100 μM reduced the expression levels of TNFα, RAF1, and p-PDGFR-β proteins, each of which has been implicated in causing treatment resistance in melanoma." (PMID 31615091, 2019). "In melanoma, macrophage-derived TNFα is a key factor responsible for the resistance to MAPK inhibitors, acting via MITF, having the capacity to regulate survival and anti-apoptotic genes." (PMID 31652660, 2019). "In melanoma cells, low levels of phosphorylation of IKKα/β were detected before TNFα treatment, and TNFα (10 ng/mL) treatment enhanced phosphorylation of IKKα/β in melanoma cells except SK-MEL-28." (PMID 31611597, 2019). "We found that compared with control cells, melanoma cells treated with TNFα or IL-1β displayed increased cell growth." (PMID 31015455, 2019). "(B and C) Expression of melanoma differentiation genes by quantitative RT-PCR at baseline or after treatment with TNFα, recombinant IL32α, IL32β, or IL32γ measured at day 3 (B) or day 7 (C)." (PMID 30953519, 2019). "It is plausible, then, that IL32 is expanded within the microenvironment as a byproduct of the feedback loop between the anti-tumor inflammatory response (marked by TNFα and IFNγ) and dedifferentiation of melanoma." (PMID 30953519, 2019). "Only increased levels of TNFα were detected in combination with ipilimumab in both melanoma cell co-cultures." (PMID 31192129, 2019). "A recent publication reported that regulation of the immunomodulatory check point programmed death-ligand 1 (PD-L1) in tumour-associated macrophages and monocytes was strongly increased by TNF in a B16 melanoma mouse model of disease." (PMID 30755793, 2019).
melanoma (continued). "The immune microenvironment represents a source of resistance to MAPK pathway inhibitors also via an increased number of tumor-associated macrophages, and TNFα and MITF (microphthalmia transcription factor) expression, observed in BRAF-mutant melanomas." (PMID 31652660, 2019). "Blocking TNF/TNFR1 signaling in vivo using targeting antibodies was able to increase the proportion of melanoma-specific CD8+ T cells in the microenvironment and delayed tumor growth." (PMID 31417576, 2019). "For example, hyperthermic perfusion of limbs with melphalane and TNF-α has been employed to reduce tumor burden in unresectable limb sarcoma or melanoma, perhaps by mitigating thermoresistance through the downregulation of HSF1-regulated HSPs." (PMID 31814876, 2019). "In an immunogenic mouse melanoma model, anti-PD-1 therapy allowed for the regression of 20% of tumors, whereas combining anti-PD-1, and anti-TNF induced the regression of 75% of them." (PMID 31417576, 2019). "Non IL32-expressing differentiated melanoma cell lines exposed to TNFα or IFNγ can be induced to express the three predominant isoforms (α, β, γ) of IL32." (PMID 30953519, 2019). "Only IFNβ is expressed in untreated melanoma cells; however, levels of secreted IFNγ and TNFα become significantly increased in the sera of melanoma patients under targeted therapy." (PMID 30850015, 2019). "As a matter of fact, in the B16 mouse melanoma model, secretion of low levels of TNF by cancer cells promoted the infiltration of tumors with myeloid cells." (PMID 31417576, 2019). "In murine (B16F-10) melanoma cells, activation of multiple caspases, pro- and anti-apoptotic proteins and pro-inflammatory cytokines (e.g., TNF-α, interleukin-1β, IL-6, IL-12p40 and NF-κB) were all shown to be involved in SFN-induced apoptosis (1–5 μM)." (PMID 31003534, 2019). "A study with a melanoma mouse model showed that treatment with both PD-1 inhibitors and TNF-α inhibitors had a better therapeutic effect than treatment with PD-1 inhibitors alone." (PMID 30646912, 2019). "Expression of IL32 in human melanoma can be induced by TNFα or IFNγ and correlates with a treatment-resistant dedifferentiated genetic signature." (PMID 30953519, 2019). "In a mouse melanoma model, we demonstrated that TNF impairs the accumulation of CD8+ T cells in tumor-draining lymph nodes and tumors in a TNFR1-dependent manner." (PMID 31727152, 2019). "In a mouse model of melanoma, concurrent treatment with anti-PD-1 and anti-TNFα led to improved anti-tumor responses." (PMID 31439050, 2019). "Increasing TNFα has been shown to promote reversible melanoma dedifferentiation through c-Jun-mediated suppression of the melanocytic differentiation marker MITF and can confer resistance to T cell therapy." (PMID 30850015, 2019). "The CSPG4-specific CAR-T cells recognized the CSPG4-positive melanoma cell line A375M and responded with the production of IL-2, TNF, and IFNγ, while the CSPG4-negative target cell line 293T was not recognized." (PMID 31426437, 2019). "The A375 melanoma cell line expresses low levels of TNF-α, and this cytokine, derived from myeloid cells, was described as fundamental for melanoma growth in vitro." (PMID 31167479, 2019). "CAR T cells and TETARs exhibited a significant TNF secretion after co-incubation with unpulsed A375M melanoma cells (expected CAR response only) in comparison to mock-electroporated cells, while no cytokine secretion was observed in TCR T cells." (PMID 31137488, 2019). "Recently, 5-aza an apoptosis-inducing agent with promising anti-melanoma effects was shown to act through the induction of TNF-α in melanoma tumor cells leading to caspase-dependent apoptosis." (PMID 29588627, 2018). "Previous studies in melanoma patients used TNFα antibodies to overcome the resistance to anti-PD-1 therapy." (PMID 30647851, 2018).
melanoma (continued). "Major focus of our study related to the apoptosis of melanoma cells is to understand the mechanism of ceramide generation by cisplatin in PKCδ deficient cell, while IRF-1 and TNFα emerged as key regulatory molecule." (PMID 30701020, 2018). "After performing GET in murine melanoma tumors, both TNFα and IL-12 mRNA levels were significantly increased, which resulted in a pronounced delay in tumor growth of 27 days and a prolonged survival time of mice." (PMID 29468364, 2018). "A recent study reported that TNFα produced by macrophages rendered melanoma cells resistant to MEK inhibition through activation of NF-κB signaling." (PMID 30042442, 2018). "Nevi and thin primary melanomas (less than < 1 mm of thickness) express low levels of IL-8, tumor necrosis factor-alpha (TNF-α), transforming growth factor-beta (TGF-β) and c-kit." (PMID 30591049, 2018). "Further, the inflammatory cytokine tumour necrosis factor alpha (TNFα) secreted by cells in the microenvironment has been shown to induce dedifferentiation in melanoma tumours." (PMID 30454027, 2018). "In the present study, cytokines secretion, evaluated by Luminex technology, showed different levels of pro-inflammatory cytokines like IL-1β, IL-8 and TNF both in melanoma cell lysates and in supernatants." (PMID 30591049, 2018). "The treatment of exogenous recombinant TNFα (50ng/ml) also increased ceramide generation in PKCδ silenced A375 melanoma cells." (PMID 30701020, 2018). "Deletion of Chi3l1 in T cells in mice show reduced melanoma lung metastasis with increased IFNγ and TNFα-producing T cells in the lung." (PMID 29403003, 2018). "For example, UV irradiation-induced metastasis of primary melanoma was shown to be mediated by activated neutrophils that prompt angiogenesis and TNF-dependent migration of melanoma cells towards vascular endothelial cells, both in vitro and in vivo." (PMID 30200242, 2018). "TNF-α mRNA expression in melanoma-bearing mice (M) was reduced by 83% compared to control mice while TLR-4 and TLR-2 mRNA expression was suppressed by 70% and 35%, respectively compared to control mice." (PMID 29588627, 2018). "Further studies revealed that increased ASMase expression is dependent on TNFα and TNFαR1 expression on cisplatin treatment in PKCδ silenced melanoma cells." (PMID 30701020, 2018). "Serum TNF-α levels in the zymosan-treated melanoma (ZM) group were elevated compared to those observed in the C and M groups." (PMID 29588627, 2018). "On the contrary, primary melanomas at more advanced stage (> 1 mm of thickness) show up-regulation of IL-1α, IL-1β, IL-8, TNF-α, TGF-β and granulocyte-macrophage colony stimulating factor (GM-CSF)." (PMID 30591049, 2018). "Our results showed that in NSCLC the blockade of TNFα would favor the tumor growth and probably would show a completely different effect as in melanoma treatment and which further on demonstrated the dual effects of TNFα in different cancer types." (PMID 30647851, 2018). "TNF-α mRNA levels in peritoneal macrophages from melanoma-bearing mice (M) were decreased compared to control animals but were significantly elevated in zymosan-treated control animals (Z) and in zymosan-treated melanoma-bearing animals (ZM) (all P < 0.05)." (PMID 29588627, 2018). "A number of studies have showed that IL-10 reduces the synthesis level of VEGF, TNF-α, or MMP-9, which leads to a prevention of angiogenesis associated with the growth of the tumour; such as melanoma and prostate cancer." (PMID 30458011, 2018). "It was observed that cisplatin in PKCδ deficient B16F10 melanoma cells were unable to induce the expression of IL-12 and IFN-γ, whereas it increased the expression of TNFα." (PMID 30701020, 2018). "We then performed meta-analysis of the relationship between TNF-α rs1800629 and the risk of skin cancer, including SSCC, SBCC, and melanoma." (PMID 28881857, 2017).
melanoma (continued). "Macrophages are the major producers of the proinflammatory cytokine TNF, and we and others have shown that TNF not only is important for melanoma growth and invasion, but also contributes to tolerance to MAPK inhibition." (PMID 28450382, 2017). "Smac mimetics that antagonize BIRC3 activity have also demonstrated activity against melanoma cell lines when combined with TNF-α." (PMID 27074575, 2017). "In fact, Landsberg and coworkers studying an experimental melanoma model have provided evidence that the T-cell-driven-inflammatory response—mainly mediated by TNF-α—exerts an inhibitory effect on melanoma cell differentiation." (PMID 29156643, 2017). "Taken together, our results provide the first proof-of-concept of combining anti-PD-1 and anti-TNF to fight melanoma and putatively other cancers." (PMID 29273790, 2017). "Studies show surgical stress results in a reduction in the number of CD8+ T cells that produce cytokines (IFNγ, TNFα, and Granzyme B) in response to TAA (adenovirus expressing melanoma tumor-associated antigen)." (PMID 29201900, 2017). "Though serial passages, TNF-induced melanoma cells were shown to be capable of extensive self-renewal." (PMID 29156643, 2017). "We performed a meta-analysis to assess the relationship between single nucleotide polymorphisms in the TNF-α promoter region (rs1800629 and rs361525) and susceptibility to squamous cell carcinoma (SCC), basal cell carcinoma (BCC) and melanoma." (PMID 28881857, 2017). "Strikingly, an immune escape gene signature was evidenced in melanoma samples exhibiting high TNF expression, suggesting that TNF is part of a gene network, which leads to immune suppression in human melanoma." (PMID 29273790, 2017). "For neurons, prostate cancer, and melanoma, TNFα-induced activation of NF-κB has been shown to help dedifferentiate somatic cells into cells with stem-cell-like properties that assist in repairing epithelial injury." (PMID 29254234, 2017). "Our study demonstrates that TNF potently induced TIM-3 expression on CD8+ TILs co-cultured with autologous melanoma cells from metastatic melanoma patients." (PMID 29273790, 2017). "Collectively, our data demonstrate for the first time that TNF is a potent inducer of TIM-3 expression on CD8+ TILs both in experimental mouse melanoma and in vitro using TILs isolated from metastatic melanoma patients." (PMID 29273790, 2017). "Here, we identified PrP as being critical for tumor necrosis factor (TNF) α-triggered signaling in a human melanoma cell line, M2, and a pancreatic ductal cell adenocarcinoma cell line, BxPC-3." (PMID 28900035, 2017). "CD4+ tumor-infiltrating lymphocytes (TILs) in melanoma produce TNF, which inhibits cytotoxic CD8+ T-cell responses." (PMID 29273790, 2017). "S4428z-equipped T-cells secreted significant amounts of IFNγ, IL2, and TNFα when cocultured with cells from the primary melanoma culture M#3 (e.g., 3,987, 343, and 1,027 pg/ml, respectively), underscoring the potential clinical relevance of our approach." (PMID 29085357, 2017). "It was also reported that melanoma cells reversibly downregulate melanocytic lineage antigens responding to TNF-α produced by CTL following therapy." (PMID 28233863, 2017). "IL-10 has been shown to inhibit the production of IL-1, IL-6, IL-8, TNF-α and forced expression of IL-10 suppressed VEGF and MMP-9, secreted by tumor-associated macrophages in melanoma model." (PMID 29219852, 2017). "In the WM35 melanoma cells, TNF-α as well as TRAIL expression and oxidative damage were strongly increased by the combined GaPc-PDT associated with Metformin, as opposed to single GaPc-PDT." (PMID 28278159, 2017). "Our recent work has highlighted that TNFR1-dependent TNF signalling impairs the accumulation of CD8+ tumor-infiltrating T lymphocytes (CD8+ TILs) in mouse melanoma." (PMID 29273790, 2017).
melanoma (continued). "Vedolizumab was chosen for this purpose as infliximab was considered excessive in relation to irAE severity; moreover, there is an unclear relationship between anti-TNFα therapy and melanoma." (PMID 28204866, 2017). "Secondly, we assessed activation of each T-lymphocyte clone in response to melanoma cell lines treated +/− IFNγ, by measuring TNFα secretion." (PMID 26885372, 2016). "In both cases the percentage of activated T-lymphocytes (secreting TNFα) was increased following incubation of melanoma cells with IFNγ." (PMID 26885372, 2016). "Contact of DCs with SNs of melanoma cells whose cell death was modulated by zVAD-fmk resulted in an increased TNFα secretion." (PMID 25973681, 2015). "Next, we determined how MITF suppression changes the global responsiveness of human MZ7 melanoma cells (MITFhigh group) to increasing amounts of TNF-α." (PMID 26530832, 2015). "We observed the same increase in TNFα secretion after treatment with other drugs used in melanoma treatment, such as dabrafenib (BRAFi) or trametinib and PD0325901 (MEK inhibitors)." (PMID 27462428, 2015). "Although melanoma epimutations have not been identified so far, abnormal methylation levels of TNF and TNFRSF10C genes have been associated with melanoma risk." (PMID 26106605, 2015). "The National Cancer Institute of the USA (NCI) has used the ligand-targeting properties of the RGD4C-AAVP to deliver tumor necrosis factor alpha (TNF-α) to the angiogenic vasculature of human melanoma xenografts in nude mice." (PMID 25606974, 2015). "All together, these results demonstrate for the first time the pivotal role of CD271 in melanoma acquired resistance and highlights the role of of TNFα/NF-κB signaling pathway in the maintenance of CD271 expression and cell resistance in BRAFi-treated cells." (PMID 27462428, 2015). "We first dosed TNFα secreted by sensitive vs resistant melanoma cells and showed that TNFα was increased in resistant cells." (PMID 27462428, 2015). "Released pro-inflammatory cytokines such tumour necrosis factor (TNF)-α induced dedifferentiation of the melanoma cells and thereby suppressed the expression of the melanocytic target antigen gp100." (PMID 26530832, 2015). "Not surprisingly, MITF expression is also regulated through the microenvironment, and macrophages can induce MITF expression in melanoma cells through secreted TNF‐α." (PMID 25818589, 2015). "Next, we asked how inflammatory TNF-α signalling interconnects with the identified MITF/c-Jun antagonism in melanoma cells." (PMID 26530832, 2015). "This regulation has gained relevance in the context of microenvironment signalling from immune cells, where macrophage‐derived TNF‐α appears to be required for the maintenance of MITF expression during melanoma growth." (PMID 25818589, 2015). "Tumor necrosis factor α (TNF-α) is used in isolated limb perfusion of locally advanced melanoma or soft tissue sarcoma due to its capacity to induce tumor cell apoptosis and subsequent immunological anti-tumor responses." (PMID 26107883, 2015). "Vemurafenib activates NF-κB signaling pathway by stimulating TNFα secretion by treated melanoma cells themselves, leading to autocrine TNFα signaling." (PMID 27462428, 2015). "As IL-1β and IL-6 are bona fide TNF-α targets, this delineates a potent feed-forward mechanism of melanoma dedifferentiation instigated by TNF-α." (PMID 26530832, 2015). "Earlier studies have shown that, in melanoma cell lines, 1-alpha, 25-Dihydroxyvitamin D3 (calcitriol) repressed IL-8 promoter activity that was induced by tumor necrosis factor-alpha (TNF-alpha)." (PMID 26504364, 2015). "Given the marked effects of RIPK3 deficiency on NKT cell production of TNF and IFN-γ in the melanoma model, we next examined RIPK3 involvement in a model of inflammatory tissue damage." (PMID 26381214, 2015).